CBX5 (chromobox 5)
Description:
Component of heterochromatin that recognizes and binds histone H3 tails methylated at 'Lys-9' (H3K9me), leading to epigenetic repression. In contrast, it is excluded from chromatin when 'Tyr-41' of histone H3 is phosphorylated (H3Y41ph). Also recognizes and binds histone H1.4 methylated at 'Lys-26' (H1.4K26me). Excluded from chromatin when histone H1.4 is Simultaneously methylated at Lys-26 (H1.4K26me) and phosphorylated at Ser-27 (H1.4S27Ph). May contribute to the association of heterochromatin with the inner nuclear membrane by interactions with the lamin-B receptor (LBR). Involved in the formation of kinetochore through interaction with the MIS12 complex subunit NSL1. Required for the formation of the inner centromere.
Synonyms: HP1A; HP1Hs-alpha; HP1; HP1-ALPHA; HP1alpha; HEL25
Tractability: PROTAC: UniProt records ubiquitination sites on it; ubiquitination databases record sites on it; its protein half-life has been measured; a small molecule that binds it is known.
Target class: Epigenetic regulator; Reader; Methyl-lysine/arginine binding protein; Chromodomain
Gene: Protein-coding gene on chromosome 12 (54,230,942 to 54,280,133, reverse strand). Ensembl gene ENSG00000094916.
Subcellular location: Nucleus; Chromosome; Chromosome, centromere
Subcellular location (Human Protein Atlas): Nucleoplasm
Pathways (Reactome):
Gene expression (Transcription): Regulation of endogenous retroelements by KRAB-ZFP proteins; Transcriptional Regulation by E2F6
Hemostasis: Factors involved in megakaryocyte development and platelet production
Metabolism of proteins: SUMOylation of chromatin organization proteins
Gene Ontology:
Molecular function: histone H1K26me1 reader activity; histone H1K26me2 reader activity; histone H3K9me2/3 reader activity; identical protein binding; protein binding; protein-containing complex binding; ribonucleoprotein complex binding; chromatin binding; DNA-binding transcription factor binding; protein-macromolecule adaptor activity; histone deacetylase binding; histone reader activity
Biological process: chromosome condensation; DNA damage response; heterochromatin formation; heterochromatin organization; negative regulation of DNA-templated transcription; negative regulation of transcription by RNA polymerase II; protein localization to heterochromatin
Cellular component: chromosome; chromosome, telomeric region; heterochromatin; nucleolus; nucleoplasm; nucleus; PML body; protein-containing complex; ribonucleoprotein complex; site of DNA damage; histone deacetylase complex; histone methyltransferase complex; nuclear envelope; pericentric heterochromatin; transcription repressor complex; chromocenter; chromosome, centromeric region; kinetochore
Genetic constraint (gnomAD): Loss-of-function variants: 6 observed, 16.31 expected, observed/expected ratio (o/e) 0.37, 90% interval 0.2 to 0.73. The upper end of that interval is the gene's LOEUF score, 0.73, which puts it in group 2 of 6, group 1 being the genes least tolerant of losing a copy. Missense variants: 85 observed, 187.22 expected, observed/expected ratio (o/e) 0.45, 90% interval 0.38 to 0.54. Synonymous variants: 61 observed, 65.7 expected, observed/expected ratio (o/e) 0.93, 90% interval 0.75 to 1.15.
Homologues: Orthologues: macaque CBX5 (100% identical), pig CBX5 (100% identical), dog CBX5 (99% identical), guinea pig CBX5 (99% identical), rabbit CBX5 (99% identical), mouse Cbx5 (98% identical), rat Cbx5 (98% identical), chimpanzee CBX5 (93% identical), tropical clawed frog cbx5 (81% identical), zebrafish cbx5 (70% identical), Caenorhabditis elegans hpl-1 (30% identical), Caenorhabditis elegans set-31 (27% identical). Paralogues in human: CBX1 (62% identical), CBX3 (60% identical), CBX6 (25% identical), CBX2 (25% identical), CBX4 (24% identical), CBX8 (23% identical), CBX7 (19% identical), NPTXR (9% identical).
Diseases named in the same sentence as CBX5 in open-access papers:
CBX5 is named in the same sentence as 68 diseases in open-access papers, as found by Europe PMC text mining. Sharing a sentence is not in itself a finding about the gene and the disease. The quoted sentences say what the papers report.
breast carcinoma (17 papers, 2012 to 2025). "In breast cancer, the expression level of CBX5 and encoded HP1α correlates with both clinical outcome in terms of patient survival and clinical data in terms of tumor size and stage of this disease." (PMID 26791953, 2016). "Introduction of mutation in a USF/C-MYC recognition site upstream for the CBX5 transcriptional start site diminished differential expression in invasive versus poorly invasive breast cancer cells." (PMID 26791953, 2016). "CBX5 has been found to aberrantly express in renal cell carcinoma, breast cancer, and acts as an oncogene." (PMID 34895048, 2021). "CBX5 expression has been found in multiple cancers including breast cancer, gastric cancer, and lung cancer." (PMID 34395271, 2021). "In breast cancer patients, high CBX5 expression is correlated with decreased survival and the increased occurrence of metastasis over time." (PMID 33014884, 2020). "Similar to CBX3, over-expression of CBX5 was found in many kinds of malignancies, such as pancreatic cancers, breast cancers and lung cancers." (PMID 30481161, 2018). "TSA treatment and Chromatin Immunoprecipitation (ChIP) were performed to investigate the chromatin structure along CBX5 in breast cancer cells." (PMID 26791953, 2016). "Another possibility in breast cancer cells to mechanistically disconnect generation of HP1α from the functionally shared promoter architecture for CBX5 and hnRNPA1 is the use of downstream alternative promoters producing HP1α coding transcripts." (PMID 26791953, 2016). "This is illustrated by the CBX5 down-regulation in metastatic breast cancer cells compared to poorly invasive breast cancer cell lines whereas hnRNPA1 is relatively evenly expressed in both types of cell lines." (PMID 26791953, 2016). "Analysis of the transcriptional regulation of CBX5 in breast cancer cells have been performed with a resulting mapping of cis-elements and trans-factors." (PMID 26791953, 2016). "In this study, we have shown that the decrease in HP1α expression in metastatic breast cancer cells involves promoter downstream sequences of the HP1α encoding CBX5 gene." (PMID 26791953, 2016). "This resulted in the identification of a USF/C-MYC recognition site upstream for the CBX5 transcriptional start site to be involved mediating differential expression in invasive versus poorly invasive breast cancer cells." (PMID 26791953, 2016). "The decrease in CBX5 expression level in metastatic breast cancer cells correlates with decreased presence of H3K36me3, RNA polymerase II (Pol-II), and basal transcription factors at the promoter." (PMID 26791953, 2016). "Inverse correlation between STET and HP1α coding CBX5 mRNA expression was observed in breast cancer cell lines and tissue samples from breast cancer patients." (PMID 26791953, 2016). "Transient transfection and transposon mediated integration of dual-reporter mini-genes containing the bi-directional hnRNPA1 and CBX5 promoter was performed to investigate transcriptional regulation in breast cancer cell lines." (PMID 26791953, 2016). "Cbx5 has been shown to be up-regulated in the breast cancer cell line MCF7 with corresponding increase in protein levels." (PMID 22670227, 2012). "However, in metastatic colon cancer, thyroid carcinoma, and breast cancer cells, CBX5 expression was found to be downregulated compared to that in poorly invasive or non-metastatic cells." (PMID 34395271, 2021). "Thus, for hnRNPA1 and CBX5 evolution must have adapted regulatory mechanisms un-coupling the expression of the two genes under certain cellular environments e.g. during breast cancer metastasis." (PMID 26791953, 2016). "Also, CBX5 promoter binding of the transcription factor YY1 is involved in regulating the differential expression levels in breast cancer cells." (PMID 26791953, 2016).
breast carcinoma (continued). "The expression analyses supported existence of independent regulation of CBX5 and hnRNPA1 transcription in breast cancer cells with a concordant up-regulation of the two genes from normal cells to cancer cells and subsequently specific down-regulation of CBX5 in metastatic cells." (PMID 26791953, 2016). "Here, we address the regulation of CBX5 in human breast cancer." (PMID 26791953, 2016). "Finally, expression of hnRNPA1 and CBX5 mRNA isoforms were measured by quantitative reverse transcriptase PCR (qRT-PCR) in breast cancer tissue samples." (PMID 26791953, 2016). "Besides, down-regulation of CBX5 resulted in mitotic defects of breast cancer cell lines Hs578T." (PMID 30481161, 2018). "Thereby, the current results could fit a model wherein reduced CBX5 transcriptional quality in metastatic breast cancer cells mediated by downstream elements e.g. through impaired transcriptional re-initiation and elongation, results in relative increased inclusion of the STET composite exon." (PMID 26791953, 2016). "Human HP1 proteins, HP1α/CBX5, HP1β/CBX1, and HPγ/CBX3, correlated with proliferation, invasion, and metastasis by regulating gene expression in human breast cancer cells." (PMID 33082469, 2020). "Inverse correlation between STET and HP1α coding mRNA expression, transcribed from the canonical CBX5 bi-directional promoter was observed in both breast cancer cell lines and samples from breast cancer patients." (PMID 26791953, 2016). "The CBX5, a member of chromobox (CBX) family, was suggested to function as a prognostic biomarker and potential target for various cancers; including gastric cancer, breast cancer, and lung cancer." (PMID 33785763, 2021). "CBX5 was upregulated at the mRNA and protein levels in breast cancer cells compared with non-cancerous cells." (PMID 33082469, 2020). "Also, other CBX family members like CBX3, CBX4, CBX5, CBX6, CBX7 and CBX8 express different patterns in breast cancer compared with other cancer types cells." (PMID 29190923, 2017). "CBX5 is down-regulated at the transcriptional and protein level in metastatic compared to non-metastatic breast cancer." (PMID 26791953, 2016). "The expression of CBX5 transcripts with coding potential for HP1α is decreased in invasive and migratory MDA-MB-231 breast cancer cells compared to the poorly invasive and migratory MCF-7 breast cancer cells." (PMID 26791953, 2016). "However, CBX5 was downregulated in highly invasive or metastatic breast cancer cell lines compared with weakly invasive or non-metastatic cells, which suggested that CBX5 is a metastatic suppressor in the invasion process." (PMID 33082469, 2020). "In this study, we find the differential expression of CBX5 in metastatic versus non-metastatic breast cancer cells requires a decoupling from the bi-directional promoter architecture of CBX5 and hnRNPA1, and investigate sequences downstream of the CBX5 promoter as possible mediators hereof." (PMID 26791953, 2016). "Based on the presented expression analyses, we conclude that the observed specific down-regulation of the CBX5 transcriptional orientation in MDA-MB-231 breast cancer cells, and thereby HP1α protein, most likely is not strictly promoter dependent, but involves promoter downstream sequences." (PMID 26791953, 2016). "The novel HP1α encoding transcriptional isoforms, V1 and V2, could participate in generating relatively higher HP1α expression in non-metastatic MCF7 breast cancer cells without requirement of specific CBX5 to hnRNPA1 transcriptional enhancement from the bi-directional promoter." (PMID 26791953, 2016).
lung carcinoma (15 papers, 2017 to 2025). "We observed a good correlation between miR-200c-3p expression and its potential target CBX5 in lung cancer cell lines." (PMID 39414799, 2024). "Especially, GGTA1P, RP11‐284F21.9, hsa‐miR‐150‐5p and CBX5 showed statistical significance as independent prognostic factors, whereas these RNAs had crossover in KM survival analysis to separate lung cancer patients’ survival outcomes." (PMID 32860342, 2020). "In lung cancer patients, mRNA expression of CBX5 was significantly higher in the tumor samples as well as in the metastatic lesions and was associated with worse OS." (PMID 30481161, 2018). "A recent experiment on CBX5 identified it as a putative target in lung cancer through a scalable network-based target identification process." (PMID 28587194, 2017). "Furthermore, CBX5 is known to regulate the stem cell-like phenotype of lung cancer cells and can serve as a prognostic marker for lung cancer, also playing a key role in the differentiation of endothelial progenitor cells into endothelial cells." (PMID 39988672, 2025). "Moreover, Chromobox Protein Homolog 5 (CBX5) is elevated in colorectal cancer and supports tumor stem-like properties in lung cancer, and SUMF2 is highly mutated in colorectal cancer." (PMID 35624824, 2022). "CBX5 was significantly overexpressed in lung cancer, lymphoma, pancreatic cancer and other cancer." (PMID 36140750, 2022). "CBX5 regulates the stem-like properties of lung tumor stem-like cells (TSLCs) and is predictive of lung cancer prognosis, as determined by the identification of target genes based on modeling epistatic signaling mechanics via a predictive and scalable network-based survival model." (PMID 33014884, 2020). "In lung cancer, the expression of CBX1, CBX2, CBX3, and CBX5 was up-regulated, while CBX7 was down-regulated." (PMID 34966411, 2021).
gastric cancer (9 papers, 2011 to 2022). A primary or metastatic malignant neoplasm involving the stomach. "The expression of CBX5 was elevated in gastric cancer tumor tissues and it promoted cell proliferation, migration, and invasion." (PMID 33785763, 2021). "In previous research, it was disclosed that CBX5 accelerated cell proliferation and invasion in gastric cancer, indicating the CBX5 exerted an carcinogenic function in this disease." (PMID 33185692, 2020). "High expression of CBX5 was detected in gastric cancer and can promote cell migration and invasion." (PMID 35155439, 2022). "Additionally, similar protein expression levels of CBX5/8 were observed between normal tissues and gastric cancer tissues." (PMID 35969177, 2022). "It was found that the microRNA-758-3p–CBX5 axis promoted tumor progression in gastric cancer (GC)." (PMID 36140750, 2022). "The transcription levels of CBX2, CBX3, CBX4 and CBX5 were significantly enhanced, whereas the mRNA level of CBX7 was decreased in gastric cancer tissues compared with normal tissues." (PMID 34117289, 2021). "Expression of ITGB5, TYMS, MYB, APOC1, CBX5, PLA2G2A, and KIF20A which is up-regulated in human gastric cancer tissues, was significantly decreased by vorinostat." (PMID 21931799, 2011). "Of these 12 genes, 7 genes highly expressed in gastric cancer tissues were down-regulated (ITGB5, TYMS, MYB, APOC1, CBX5, PLA2G2A, KIF20A) and 5 low-expressed genes were up-regulated after vorinostat treatment (SCGB2A1, TCN1, CFD, APLP1, NQO1." (PMID 21931799, 2011). "were the first to confirm the high expression levels of HP1-α (CBX5) in gastric cancer tissues, and then revealed that HP1-α (CBX5) could promote the proliferation, migration, and invasion, of gastric cancer cells in vitro." (PMID 34046352, 2021). "Moreover, gene expression analysis of gastric cancer identified a collection of genes (ITGB5, TYMS, MYB, APOC1, CBX5, PLA2G2A, and KIF20A) whose expression was elevated in gastric tumor tissue and downregulated more than 2-fold by vorinostat treatment in gastric cancer cell lines." (PMID 21931799, 2011).
glioma (5 papers, 2022). A benign or malignant brain and spinal cord tumor that arises from glial cells (astrocytes, oligodendrocytes, ependymal cells). "Further studies are necessary to clarify whether the mechanisms of the tumorigenic effect of CBX5 in LUAD are similar to those in glioma." (PMID 36263018, 2022). "It has been reported that CBX5 and H3K9me3 are enriched in the FAS and PUMA promoters in glioma, indicating that CBX5 could suppress apoptotic activators by sustaining the methylation level of H3K9me3." (PMID 36263018, 2022). "LINC02381 promoted glioma cell growth via CBX5 by rescue experiment." (PMID 35962317, 2022). "CBX1-3, CBX5, and CBX8 were significantly elevated in the brain and CNS cancers." (PMID 36034290, 2022).
thyroid cancer (4 papers, 2020 to 2024). "Regarding CBX5, its upregulation has been associated with increased cell proliferation and poor clinical prognosis; furthermore, its downregulation was linked to a higher invasive potential of cancer cells in metastatic cells of colon cancer and thyroid carcinoma compared with non-metastatic cells." (PMID 36292141, 2022).
colon cancer (3 papers, 2020 to 2022). "With regard to CBX5, all six host immune cells have a positive correlation in colon cancer patients, while the infiltration of B cells, CD8+ T cells and neutrophils have a positive correlation with CBX5 in rectal cancer patients." (PMID 33014884, 2020).
ovarian carcinoma (3 papers, 2020 to 2022). A malignant neoplasm originating from the surface ovarian epithelium. "Nevertheless, the prognostic value of the other five CBXs family members for predicting OS and PFS in ovarian cancer patients was either irrelevant (CBX5 and CBX8) or inconsistent (CBX4, CBX6, and CBX7)." (PMID 35155439, 2022). "In addition, interacting with BRD4, CBX5 can inhibit DNA damage response in ovarian cancer." (PMID 36140750, 2022). "However, the results showed that the prognostic significance of CBX4-8 mRNA expression for predicting OS and PFS in all patients with ovarian cancer was inconsistent (CBX4, CBX6 and CBX7) or irrelevant (CBX5 and CBX8)." (PMID 32742466, 2020).
pancreatic cancer (3 papers, 2018 to 2022). "Bioinformatic analyses through the GEPIA web tool revealed that CBX3, CBX1, and CBX5 were significantly overexpressed in the pancreatic cancer tissues than those in non-malignant pancreatic tissues (P < 0.01)." (PMID 35637952, 2022). "It is worth noting that the mRNA levels of CBX1, CBX3, CBX5 and CBX8 were elevated in pancreatic cancer tissues compared with non-malignant pancreatic tissues." (PMID 35637952, 2022).
prostate carcinoma (3 papers, 2024 to 2025). A carcinoma that arises from epithelial cells of the prostate gland. "Then we further clarified the expression of CBX family members in prostate cancer, which result showed that CBX5, CBX6 and CBX7 were significantly down-regulated in prostate cancer tissues, while CBX3, CBX2, CBX4 and CBX8 was notably up-regulated." (PMID 40861818, 2025).
renal cell carcinoma (3 papers, 2020 to 2023).
gastric tumor (2 papers, 2011 to 2019). "In the gastric tumors, many of these genes are regulated by ETS2, BMP4, and TGFB1 and by the kinases MAPK1(ERK) and CCNK and the transcription regulators E2F, CBX5, and CCND1." (PMID 31584998, 2019).
leukemia (2 papers, 2009 to 2024). A malignant (clonal) hematologic disorder, involving hematopoietic stem cells and characterized by the presence of primitive or atypical myeloid or lymphoid cells in the bone marrow and the blood. "CBX5 was reported to had higher expression in high than in low c-Kit leukemia stem cell populations, and elevated CBX5 expression was associated with increased expression of RBMX and RBMXL1, which maintain the chromatin state essential for the survival of acute myeloid leukemia cells." (PMID 38798352, 2024).